CREG1 (cellular repressor of E1A stimulated genes 1)
Description:
May contribute to the transcriptional control of cell growth and differentiation. Antagonizes transcriptional activation and cellular transformation by the adenovirus E1A protein. The transcriptional control activity of cell growth requires interaction with IGF2R.
Synonyms: CREG
Tractability: Small molecule: it has a high-quality binding pocket. Antibody: UniProt places it where antibodies can reach, with high confidence; its Gene Ontology location is reachable by antibodies, with high confidence; UniProt predicts a signal peptide or a membrane-spanning region. PROTAC: ubiquitination databases record sites on it; its protein half-life has been measured.
Gene: Protein-coding gene on chromosome 1 (167,529,117 to 167,553,822, reverse strand). Ensembl gene ENSG00000143162.
Subcellular location: Secreted
Subcellular location (Human Protein Atlas): Golgi apparatus; Vesicles; Microtubules; Predicted to be secreted
Pathways (Reactome):
Immune System: Neutrophil degranulation
Gene Ontology:
Molecular function: insulin-like growth factor receptor binding; transcription corepressor activity
Biological process: autophagy; endocytosis; lysosomal lumen acidification; lysosome organization; regulation of transcription by RNA polymerase II; negative regulation of DNA-templated transcription
Cellular component: endosome; extracellular exosome; extracellular region; lysosome; azurophil granule lumen; cytoplasm; endomembrane system; transcription regulator complex
Genetic constraint (gnomAD): Loss-of-function variants: 14 observed, 11.59 expected, observed/expected ratio (o/e) 1.21, 90% interval 0.79 to 1.79. The synonymous counts are far from expectation, so gnomAD's model fits this gene poorly and the ratio says little. Missense variants: 247 observed, 195.92 expected, observed/expected ratio (o/e) 1.26, 90% interval 1.14 to 1.4. Synonymous variants: 130 observed, 88.03 expected, observed/expected ratio (o/e) 1.48, 90% interval 1.28 to 1.71.
Homologues: Orthologues: chimpanzee CREG1 (99% identical), macaque CREG1 (97% identical), dog CREG1 (87% identical), rabbit CREG1 (85% identical), guinea pig CREG1 (81% identical), pig CREG1 (80% identical), mouse Creg1 (77% identical), rat Creg1 (77% identical), tropical clawed frog creg1 (55% identical), zebrafish creg1 (48% identical), Drosophila melanogaster CREG (27% identical). Paralogues in human: CREG2 (34% identical).
Diseases named in the same sentence as CREG1 in open-access papers:
CREG1 is named in the same sentence as 54 diseases in open-access papers, as found by Europe PMC text mining. Sharing a sentence is not in itself a finding about the gene and the disease. The quoted sentences say what the papers report.
Insulin resistance (6 papers, 2017 to 2024). Increased resistance towards insulin, that is, diminished effectiveness of insulin in reducing blood glucose levels. "CREG1 haploinsufficient and liver-specific knockout mice are susceptible to high fat diet-induced obesity, hepatic steatosis and insulin resistance." (PMID 30416997, 2018). "Recent reports show that CREG1 hampers diet-induced obesity and hepatic steatosis in mice, and its deletion resulted in insulin resistance." (PMID 32385587, 2021). "The loss of CREG1 leads to early embryonic death, as it is essential for early myocardial development, and CREG1 heterozygous mice are susceptible to diet-induced obesity (DIO) and insulin resistance." (PMID 33525404, 2021). "This increase in serum CREG1 level may indicate the progress of resistance to CREG1, such as insulin resistance, with age." (PMID 33525404, 2021). "Based on these findings, we tested the hypothesis that CREG1 might suppress development of obesity and insulin resistance by inhibiting inflammatory responses." (PMID 28459882, 2017). "Overexpression of CREG1 increases phosphorylation of InsR and its downstream effectors Akt and GSK-3beta, improving insulin resistance." (PMID 39639394, 2024). "In this study, we demonstrate for the first time that haplodeficiency of Creg1 exacerbated HFD-induced obesity, insulin resistance and dyslipidemia." (PMID 28459882, 2017). "Creg1 haploinsufficiency also exacerbated HFD-induced liver steatosis, dyslipidemia and insulin resistance." (PMID 28459882, 2017). "It’s not surprisingly to see that Creg1+/- mice with such an obvious obese phenotype showed exacerbated insulin resistance indicated by increased fasting glucose and insulin level, higher HOMA-IR scores, lager AUC of GTT and ITT." (PMID 28459882, 2017). "In this study, we show that haplodeficiency of Creg1 exacerbated high fat diet (HFD)-induced obesity, insulin resistance and dyslipidemia without affecting food consumption, suggesting an imbalance between calorie intake and expenditure." (PMID 28459882, 2017).
Obesity (6 papers, 2017 to 2025). Accumulation of substantial excess body fat. "In the analysis of Creg1 heterozygous mice, we unexpectedly observed that they developed obesity as they get older." (PMID 28459882, 2017). "Furthermore, administration of the recombinant form of CREG1 stimulates the differentiation of brown adipocytes and ameliorates diet-induced obesity in mice." (PMID 40674409, 2025). "An examination of the effects of CREG1 on energy metabolism in adipocyte P2 (aP2)-CREG1-transgenic (Tg) mice revealed that CREG1 overexpression stimulates brown fat thermogenesis and prevents diet-induced obesity." (PMID 40674409, 2025). "Furthermore, CREG1 is elevated in the serum and liver of aged mice, age-related obesity and renal dysfunction are ameliorated in adipocyte P2-CREG1 transgenic mice." (PMID 35280676, 2022). "Moreover, CREG1 also stimulates brown adipocyte formation and ameliorates diet-induced obesity in mice." (PMID 35280676, 2022). "This inhibitory effect of CREG1 on lipolysis may raise the concern that it should produce a lean phenotype instead of obesity observed in Creg1 haplodeficiency mice challenged with HFD." (PMID 28459882, 2017). "Our data showed that Creg1+/- mice exhibited a more prominent obesity phenotype with no change in food intake compared with WT controls when challenged with HFD." (PMID 28459882, 2017).
embryonal carcinoma (5 papers, 2015 to 2024). A non-seminomatous malignant germ cell tumor characterized by the presence of large germ cells with abundant cytoplasm resembling epithelial cells, geographic necrosis, high mitotic activity, and pseudoglandular and pseudopapillary structures formation. "Cell division and proliferation protein CREG1, a secreted glycoprotein, has been reported as cellular repressor inhibiting cell proliferation and enhancing cell differentiation in human embryonic carcinoma cells." (PMID 25693162, 2015).
Hepatic steatosis (5 papers, 2018 to 2023). Steatosis is a term used to denote lipid accumulation within hepatocytes. "Therefore, we further determined the effect of CREG1 deficiency on hepatic steatosis." (PMID 35280676, 2022). "Several groups have also demonstrated that CREG1 overexpression protects against cardiac hypertrophy and fibrosis in the mouse heart and inhibits hepatic steatosis in the mouse liver." (PMID 33525404, 2021). "We also demonstrated that the overexpression of CREG1 in adipose tissue stimulated brown adipocyte formation and ameliorated DIO in adipocyte P2 (aP2)-CREG1 transgenic (Tg) mice, in which the progression of fatty liver and the decrease in insulin sensitivity and glucose tolerance were also improved." (PMID 33525404, 2021).
myocardial infarction (4 papers, 2019 to 2025). Gross necrosis of the myocardium, as a result of interruption of the blood supply to the area, as in coronary thrombosis. "Several studies have shown that CREG1 protects against cell death and inflammation during hepatic I/R injury 17 and myocardial infarction." (PMID 35280676, 2022). "The cellular repressor of E1A-stimulated genes 1 (CREG1), a small glycoprotein, is highly expressed in the healthy heart and has been implicated in cardiac remodeling following diabetic myocardial infarction, myocardial infarction–reperfusion (MI-R), and angiotensin-II treatment." (PMID 40004130, 2025).
diabetic cardiomyopathy (3 papers, 2023 to 2025). Diabetic cardiomyopathy is a disorder of the heart muscle in people with diabetes. "In this study, we aimed to investigate the role of CREG1 in the development of diabetic cardiomyopathy and to clarify the underlying molecular mechanisms." (PMID 37658156, 2023). "CREG1 deficiency exacerbated cardiac dysfunction, cardiac hypertrophy and fibrosis in mice with diabetic cardiomyopathy, which was accompanied by exacerbated autophagy dysfunction." (PMID 37658156, 2023). "Diabetic cardiomyopathy, a fatal complication of diabetes, can be alleviated by a protein called CREG1, according to a new study." (PMID 37658156, 2023). "To further clarify the role of CREG1 overexpression in diabetic cardiomyopathy, we used Creg1-TG and WT mice to establish DM." (PMID 37658156, 2023). "CREG1 overexpression improved cardiac function and ameliorated cardiac hypertrophy and fibrosis in diabetic cardiomyopathy by improving autophagy." (PMID 37658156, 2023). "The aim of this study was to investigate the effects and mechanisms of CREG1 in diabetic cardiomyopathy." (PMID 37658156, 2023). "Our study revealed that CREG1 could ameliorate the progression of diabetic cardiomyopathy by improving autophagy in cardiomyocytes." (PMID 37658156, 2023). "By boosting autophagy in heart cells, CREG1 could help prevent the development of diabetic cardiomyopathy." (PMID 37658156, 2023). "Our findings indicate new roles of CREG1 in the development of diabetic cardiomyopathy." (PMID 37658156, 2023). "However, whether CREG1 can improve cardiac function in diabetic cardiomyopathy through autophagy regulation remains unclear." (PMID 40004130, 2025). "However, whether CREG1 can ameliorate cardiac fibrosis and improve cardiac function in diabetic cardiomyopathy remains unknown." (PMID 37658156, 2023). "Our results showed that CREG1 expression was decreased in the myocardium during diabetic cardiomyopathy preceding cardiac dysfunction, indicating a negative correlation between the decrease in CREG1 expression and the development of diabetic cardiomyopathy." (PMID 37658156, 2023). "Additionally, CREG1 is an important cardioprotective factor, inhibiting FBXO27 expression to prevent LAMP2 protein degradation, promoting autophagy in cardiomyocytes, and alleviating diabetic cardiomyopathy." (PMID 39639394, 2024).
diabetes (2 papers, 2016 to 2024). "CREG1 has been studied rigorously in relation to glucose uptake, renal dysfunction, angiogenesis, and diabetes-related comorbidity." (PMID 38674089, 2024).
Myocardial fibrosis (2 papers, 2021 to 2023). "CREG1 deficiency exacerbated cardiac dysfunction and myocardial fibrosis in diabetic conditions." (PMID 37658156, 2023). "In contrast, improvements in cardiac function and a decrease in myocardial fibrosis were observed in CREG1-overexpressing diabetic mice." (PMID 37658156, 2023).
steatosis (2 papers, 2017 to 2022). Increased lipid within the cytoplasm of cells. "Hepatocyte-specific CREG1 deficiency aggravated ethanol-induced liver injury, apoptosis, steatosis and inflammation." (PMID 35280676, 2022). "Genetic deletion of the Creg1 gene in hepatocytes (Creg1∆hep) markedly exacerbated ethanol-induced liver injury, apoptosis, steatosis and inflammation." (PMID 35280676, 2022). "The current study showed that CREG1 improved ethanol-induced liver injury, apoptosis, steatosis, and inflammation by targeting ASK1-JNK/p38 signalling." (PMID 35280676, 2022). "In consistence with the changes of plasma lipids, the liver of Creg1+/- mice on HFD displayed severe steatosis as indicated by more and larger lipid droplets in hepatocytes compared with WT controls." (PMID 28459882, 2017).
teratocarcinoma (2 papers, 2021). A germ cell tumor characterized by the presence of an embryonal carcinoma component and a teratoma component. "This short amino acid sequence—while thought to contribute to the lack of catalytic activity in human CREG1—was found to be critical for mediating cell growth inhibition in human teratocarcinoma cell line NTERA-2." (PMID 33591270, 2021).
anemia (1 paper, 2024). A reduction in the number of red blood cells, the amount of hemoglobin, and/or the volume of packed red blood cells. "Creg1 loss causes anemia due to impaired differentiation and excessive apoptosis of erythroid cells." (PMID 38953462, 2024).
asthma (1 paper, 2024). "While our data does not include direct measures of biologic response, we observe that samples with high DNAm scores are enriched with eosinophil cells exhibiting hypermethylated sites near genes implicated in T2-high asthma and biologic drug response, including CREG1 and MIR476549,50." (PMID 39315258, 2024).
breast carcinoma (1 paper, 2021). "Taken together, the results provide consistent evidence for an inverse association of CREG1 protein levels to growth and invasion properties of PyMT breast cancer cells, i.e. a high CREG1 level suppresses the malignant cell behavior, while low CREG1 promotes it." (PMID 32385587, 2021). "Conversely, in a gain-of-function approach utilizing transgenic mice overexpressing human CTSB in breast cancer, we observed a reduced abundance of CREG1 in TIF." (PMID 32385587, 2021). "As CREG1 has been described as a proliferation suppressive protein, we assessed its effects in the context of the MMTV-PyMT breast cancer model with the conclusion that CREG1 is a cathepsin-controlled extracellular suppressor of invasive tumor growth." (PMID 32385587, 2021). "Here, we show CREG1 gain- and loss-of-function experiments in the context of the MMTV-PyMT breast cancer model." (PMID 32385587, 2021). "Therefore, we analyzed levels of secreted and intracellular (lysosomal) CREG1 in dependence of the cathepsin protease genotype of cells and breast cancer tissue." (PMID 32385587, 2021). "Hence, CREG1 was a strong candidate to explain the ameliorated phenotype of CTSB knock-out in the MMTV-PyMT breast cancer model." (PMID 32385587, 2021). "As CREG1 is degraded by cathepsin proteases, which have been shown to promote tumor progression in various genetic mouse models of human cancer including the MMTV-PyMT breast cancer model, we next addressed the role of CREG1 in growth and motility of PyMT breast cancer cells." (PMID 32385587, 2021).
epilepsy (1 paper, 2025). A brain disorder characterized by episodes of abnormally increased neuronal discharge resulting in transient episodes of sensory or motor neurological dysfunction, or psychic dysfunction. "According to the ROC curves, the expression level of key genes including CTSD, CREG1, PECAM1, ZNF101, RRM2B, MARCKSL1, and MAP2K4 demonstrated a certain accuracy in classifying epilepsy and control groups (0.7 < AUC < 0.9)." (PMID 40520613, 2025).
Glucose intolerance (1 paper, 2021). Glucose intolerance (GI) can be defined as dysglycemia that comprises both prediabetes and diabetes. "These beneficial effects of CREG1 overexpression were evaluated in aged mice in this study because normal C57BL/6 mice gained a significant amount of weight with age even under standard dietary conditions, and glucose intolerance became prominent in aged animals." (PMID 33525404, 2021).
lung adenocarcinoma (1 paper, 2021). A carcinoma that arises from the lung and is characterized by the presence of malignant glandular epithelial cells. "XH was demonstrated as a potential suppressor of p90RSK and ERK1/2 kinases, activator of cellular repressor of E1A-stimulated genes 1 (CREG) protein, and inhibitor of phosphorylation of CREG in A549 lung adenocarcinoma cells." (PMID 33923053, 2021).
melanoma (1 paper, 2019). A malignant, usually aggressive tumor composed of atypical, neoplastic melanocytes. "Similarly, the up-regulated genes in the ABCB5 CTC fractions were involved in metastasis (CALU, CYB5R1, DUSP3, CREG1, ENDOD1), tumour growth, and/or melanoma biology (H1F0, SCNA, WIPI1, TXN2)." (PMID 30769764, 2019).
myocardial hypertrophy (1 paper, 2023). "In addition, CQ exacerbated cardiac hypertrophy in response to PA stimulation, which was inhibited by CREG1 overexpression (p < 0.01)." (PMID 37658156, 2023). "In addition, resveratrol inhibited cardiac hypertrophy in the si-control+PA and si-Creg1 + PA groups (p < 0.05)." (PMID 37658156, 2023). "However, myocardial hypertrophy and fibrosis occurred in the DM group of Creg1-TG and WT mice at 24 weeks." (PMID 37658156, 2023).
non-small cell lung carcinoma (1 paper, 2022). A group of at least three distinct histological types of lung cancer, including non-small cell squamous cell carcinoma, adenocarcinoma, and large cell carcinoma. "CREG1, the cellular repressor of E1A-stimulated genes, a downstream effector of KRAS which identifies in Glycoproteomic Approach as a positive regulator of CREG1 in Non-small Cell Lung Cancer Cells." (PMID 35057823, 2022).
osteonecrosis (1 paper, 2024). A none disease characterized by death of bone tissue due to a lack of blood supply. "Our study found that CREG1 reduces the risk of developing osteonecrosis, which is consistent with other findings." (PMID 39119575, 2024). "Additionally, we also found a suggestive association of inter-alpha trypsin inhibitor heavy chain 1 (ITIH1), secreted modular calcium-binding protein 1 (SMOC1), and cellular repressor of E1A-stimulated genes 1 (CREG1) proteins with osteonecrosis risk." (PMID 39119575, 2024). "This comprehensive MR study identifies 71 plasma proteins associated with osteonecrosis, with HEBP1, ITIH1, SMOC1, and CREG1 showing potential as biomarkers of osteonecrosis." (PMID 39119575, 2024).
sarcopenia (1 paper, 2024). Progressive decline in muscle mass due to aging which results in decreased functional capacity of muscles. "We analysed the transcriptional profiles of the skeletal muscle biopsies from healthy older (N = 25) and younger (N = 26) adult men and women in GSE8479 database, and the results showed that Creg1 was associated with human sarcopenia." (PMID 38272853, 2024).
Sjogren syndrome (1 paper, 2024). An autoimmune disorder in which immune cells attack and destroy the glands that produce tears and saliva. "Lastly, rs2949661 is also shown to be associated with Sjogren’s syndrome by being an eQTL to both genes CD247 and cellular repressor CREG1 and by altering TAD interactions involving CD24784." (PMID 39289357, 2024).